CRP (C-reactive protein)
Diseases named in the same sentence as CRP in open-access papers (continued):
Sharing a sentence is not in itself a finding about the gene and the disease.
leukocytosis (continued). "Laboratory tests such as ESR and CRP are important, as leukocytosis may be present in acute osteomyelitis but may be absent in chronic osteomyelitis." (PMID 40376542, 2025). "While elevated ESR, CRP, and leukocytosis may suggest infection, their presence is not definitive, and their absence does not rule it out." (PMID 41322843, 2025). "Initial blood investigations revealed leukocytosis, with a white cell count (WCC) of 13.4 ×109/L, absolute neutrophil count (ANC) of 11.0 ×109/L, a prolonged aPTT of 78 seconds (reference: 28-40 seconds), a normal prothrombin time (PT), and a normal C-reactive protein (CRP)." (PMID 40772167, 2025). "There was no increase in leukocytosis or elevation of inflammatory markers (CRP)." (PMID 39062079, 2024). "However, preoperative blood analysis was within normal ranges, showing no marked leukocytosis, with a C-reactive protein (CRP) level of 0.6 mg/dL and an erythrocyte sedimentation rate (ESR) of 23 mm/hr." (PMID 39544553, 2024). "Postimplantation syndrome (PIS) is a systemic inflammatory response that occurs following the implantation of stents or endografts, typically characterized by fever, leukocytosis, and elevated inflammatory markers, such as C-reactive protein (CRP) in the absence of infection." (PMID 39407997, 2024). "There was no tissue diagnosis confirming malignancy, and while leukocytosis and CRP, along with central diffusion restriction, suggested an infectious etiology, multiple sets of negative blood cultures, improving leukocytosis without antibiotics, and a lack of fever argued against this." (PMID 38957514, 2024). "Infections may present with leukocytosis and elevated ESR and CRP levels." (PMID 39594253, 2024). "Nonspecific findings such as leukocytosis and elevated erythrocyte sedimentation rate and C-reactive protein (CRP) might be the only analytical features on presentation, leading to misdiagnosis." (PMID 39723325, 2024). "Also, when taking into consideration the subgroups without neonatal sepsis, our results showed that leukocytosis on day 1, CRP on day 3, and fibrinogen levels on day 2 were significantly higher in the B3 subgroup compared to the A3 subgroup (p < 0.05)." (PMID 38255436, 2024). "Although their CRP levels were elevated, there was no significant increase in leukocytosis." (PMID 38133281, 2023). "Blood analysis showed leukocytosis: white blood cell (WBC)–17.0 × 109/L (normal range: 4.0–9.8 × 109/L); eosinophils–6.0 × 109/ L (normal range: 0.0–0.7 × 109/L); neutrophils 7.8 × 109/L (normal range: 1.5–6.0 × 109/L); and elevated C-reactive protein (CRP)–89.9 mg/L (normal range: 0.0–5.0 mg/L)." (PMID 35630071, 2022). "CRP may be a nonspecific biomarker for discospondylitis—but probably more sensitive than fever, leukocytosis, neutrophilia, and hyperglobulinemia." (PMID 36290272, 2022). "Laboratory work up was significant for leukocytosis (26,000/mm3) with neutrophil predominance, microcytic anemia, low albumin, prolonged prothrombin time and International Normalized Ratio (INR), and elevated inflammatory markers including CRP, procalcitonin, ferritin and D-dimer." (PMID 36683795, 2022). "Blood tests could show no leukocytosis, and the C-reactive protein (CRP) level and erythrocyte sedimentation rate are usually normal or mildly elevated." (PMID 33920619, 2021). "Moreover, the peripheralblood inflammation markers, such as C-reactive protein(CRP), leukocytosis, leptin and IL6 do not predict presence of CE." (PMID 31710184, 2020). "Nonetheless, both leukocytosis and raised CRP are not specific to this condition." (PMID 32921316, 2020). "However, we did not measure C-reactive protein level as evidence of chronic inflammation or infection because the patients exhibited no symptoms of fever or leukocytosis that indicated a need for laboratory tests of inflammatory markers." (PMID 32566294, 2020).
leukocytosis (continued). "Among them, 84 patients were excluded: 16 patients suffered from preoperative inflammatory disease, 52 were treated with immunomodulatory medication, 14 patients had preoperative leukocytosis, one had fever above 38 °C and preoperative CRP levels were not documented for one patient." (PMID 33080990, 2020). "Laboratory tests revealed moderately elevated CRP with no leukocytosis." (PMID 31412842, 2019). "Previously, the severity of AC was predicted by assessing leukocytosis and C-reactive protein (CRP) levels according to the Tokyo Guidelines, but neither of them could be utilized to predict the DLC8." (PMID 31358829, 2019). "Blood exams showed leukocytosis (16.62 × 103/μL), elevated platelets (506 × 103/μL), ESR (99 mm/h), CRP (131 mg/L), and PCT (0.10 ng/mL), while abdominal CT scan revealed celiac-mesenteric lymphoadenopathy, splenomegaly and the presence of multiple anechoic hypoechogenic nodules of unknown origin." (PMID 31416435, 2019). "In this patient, there was an increase of ESR, leukocytosis, CRP, and acid-resistant bacteria test was negative, maybe due to error in taking sample." (PMID 31394386, 2019). "No between-group difference was found for leukocytosis or CRP at admission." (PMID 30862787, 2019). "First-line blood tests were negative, with no increase in C-reactive protein (CRP) or leukocytosis." (PMID 27142277, 2016). "However, patient had remained symptom-free and the erythrocyte sedimentation ratio and level of C-reactive protein were normal with no leukocytosis." (PMID 26782665, 2016). "Laboratorial analysis showed leukocytosis (89%, p=0.5156), with an expressive increase in CRP (p=0.5065), average of 236.10 mg/l, although both without statistical significance associated with hypoalbuminemia (p=0.0402) in 80% of patients, suggesting inflammatory response." (PMID 27759785, 2016). "Moreover, there were no clinical infection symptoms such as fever and blood test abnormalities such as increased CRP level, leukocytosis during these DMSA scans and there were not any microorganisms in the urine culture before the DMSA scans." (PMID 23610726, 2013). "Laboratory data on admission revealed mild leukocytosis, with leucocyte of 10.5 × 103/μL, mild hypochromic anemia, with hemoglobin of 12.9 g/dL, and mild inflammatory reaction, with erythrocyte sedimentation rate (ESR) of 24 mm at the first hour, C-reactive protein (CRP) of 4.0 mg/dL." (PMID 21806792, 2011). "However, a few hours later, while still under observation, worsening cervical pain and stiffness prompted referral to the ED, where laboratory tests revealed relative lymphopenia without leukocytosis or eosinophilia, and a CRP level of 11.34 mg/dL (reference range: 0-0.5 mg/dL)." (PMID 41409912, 2025). "Additionally, the mild leukocytosis and the increase in C-reactive protein could be attributed to pregnancy and not to the presence of an intra-abdominal infection." (PMID 39246860, 2024). "Notably the patient did not have leukocytosis, and his C-reactive protein (CRP) levels were normal." (PMID 35864454, 2022). "However, the general condition of this case pointed to an infectious process, evident by the cellulitis, fever (38C), purulent discharge, leukocytosis (13,500 109/ul), high CRP (42 mg/dl), and the FNA showed purulent material without cytologic signs of malignancy." (PMID 34274758, 2021). "Laboratory tests revealed a biological inflammatory syndrome with a C-reactive protein (CRP) level of 312 mg/L and leukocytosis of 13,000 / mm3, without abnormalities of liver function." (PMID 40997626, 2025). "All patients had elevated CRP and ESR, three patients had thrombocytosis with leukocytosis and one patient lacked both parameters." (PMID 40590520, 2025). "Laboratory markers are often nonspecific; leukocytosis and elevated inflammatory markers such as ESR and CRP are common, but not universal." (PMID 41293359, 2025).
leukocytosis (continued). "Based on these results, it is recommended that emergency physicians should consider a diagnosis of acute bacterial colitis when children present with fever, diarrhea, and elevated serum CRP or PCT levels, even without presenting with leukocytosis." (PMID 38397283, 2024). "Blood tests indicated elevated erythrocyte sedimentation rate (ESR), C-reactive protein (CRP), and leukocytosis levels, while cultures were negative." (PMID 39712702, 2024). "Laboratory analyses demonstrated an elevated C-reactive protein (CRP) and erythrocyte sedimentation rate (ESR) in the absence of leukocytosis." (PMID 39135811, 2024). "Regarding complementary tests, nonspecific markers of inflammation such as leukocytosis, elevated erythrocyte sedimentation rate (ESR) and C-reactive protein (CRP), as well as anemia, were frequent findings in the blood test." (PMID 37324473, 2023). "There was no leukocytosis in this patient and liver function tests were normal but ESR and CRP were high." (PMID 37920259, 2023). "Laboratory data showed increased C-reactive protein (CRP) to 28 mg/l and erythrocyte sedimentation rate (ESR) to 42 mm/h without leukocytosis." (PMID 36028914, 2022). "Our findings suggest that physicians should be aware of possible PSD in patients who complain about significant back pain and limited range of motion while CRP and/or ESR are elevated, even if leukocytosis or high body temperature is absent." (PMID 33736624, 2021). "Blood test showed increased inflammatory values (C-reactive protein (CRP) 6.2 mg/dl, normal < 0.5 mg/dl) and leukocytosis (leukocytes 21,900/μl), body temperature was initially not measured." (PMID 32072333, 2020). "Laboratory evaluation revealed no leukocytosis with normal differential, elevated sedimentation rate (ESR) at 41, and a normal C-reactive protein (CRP)." (PMID 26236753, 2014). "One of the commonly accepted diagnostic criteria for PPS is an inflammation of serous cavities, and fever or biochemical characteristics of inflammation (elevated CRP levels, accelerated ESR, leukocytosis) without the presence of systemic or local infection." (PMID 25333927, 2014). "Typical laboratory findings included increased C-reactive protein (CRP) (80.6%) and erythrocyte sedimentation rate (ESR) (96%),leukocytosis (48.4%) and thrombocytosis (40.6%) without any significant quantitative difference between complete and incomplete KD." (PMID 27643389, 2014). "Analytical study revealed an elevated C-reactive protein (CRP = 70 mg/L), no anemia or leukocytosis, acute graft dysfunction, or other abnormalities." (PMID 24558621, 2013). "Interestingly, although non-survivors showed lower PC plasma levels and higher incidence of coagulopathy, the inflammatory response in terms of CRP levels and leukocytosis was less marked in the non-survivors, which could imply a degree of immuno-paralysis in those patients." (PMID 20723255, 2010). "Laboratory studies are unhelpful in diagnosing MPAA and often indicate a non-specific leukocytosis or increased erythrocyte sedimentation rate (ESR) and C-reactive protein (CRP)." (PMID 19946535, 2009). "Notable laboratory features of the disease are increased serum levels of C-reactive protein (CRP), leukocytosis, liver dysfunction, negative results for both rheumatoid factor and antinuclear antibodies, and an increased incidence of hyperferritinemia." (PMID 18325097, 2008). "However, this was ruled out by the absence of leukocytosis, normal inflammatory markers (ESR and CRP), and a lack of systemic signs." (PMID 41356652, 2025). "Furthermore, the existence of CE is not predicted by peripheral blood inflammation markers such C-reactive protein (CRP), leukocytosis, leptin, and IL6." (PMID 39941173, 2025). "The diagnostic workup for AHOI may include laboratory tests, such as a complete blood count, which can reveal nonspecific findings like leukocytosis or thrombocytosis, and inflammatory markers, including elevated erythrocyte sedimentation rate (ESR) and CRP." (PMID 39655129, 2024).
leukocytosis (continued). "Our patient presented with mouth pain and tenderness of the left floor of the mouth tenderness on physical examination, and in their lab work, although there was no leukocytosis, ESR and CRP levels were more than double the upper limits of normal, indicating a systemic inflammatory state." (PMID 39221398, 2024). "Laboratory results for this condition are often nonspecific; infections might lead to leukocytosis, with ESR and CRP levels either within the normal range or elevated." (PMID 38674610, 2024). "Leukocytosis was low, unlike the results of the WRA group in Havana; however, indicators of subclinical inflammation in this study are higher than those found in 2014 (CRP 8.4% and AGP 19.9%)." (PMID 36982031, 2023). "He had no leukocytosis or relative neutrophilia, although he did have moderately elevated biochemical inflammatory markers, specifically erythrocyte sedimentation rate (ESR) and C-reactive protein (CRP)." (PMID 35534872, 2022). "Laboratory examination showed that the serum agglutination test (SAT) in both patients were positive (1: 640 and 1: 320) without leukocytosis, although the proportion of lymphocytes, erythrocyte sedimentation rate (ESR) and C-reactive protein (CRP) significantly increased." (PMID 35509042, 2022). "With present findings, that is, persistent fever, malaise, arthralgia, generalized lymphadenopathy, persistent leukocytosis with neutrophilia, elevated SGOT and SGPT, positive CRP, and negative ANA and RA factor, Still’s disease was suspected as it met almost all the criteria." (PMID 31472695, 2019). "The most commonly used laboratory markers, such as elevated C-reactive protein (CRP), leukocytosis, or metabolic acidosis, may be present but are non-specific and can also occur in other gastrointestinal conditions like meconium ileus or systemic inflammatory response states." (PMID 41007847, 2025). "We did not record assessments of inflammation (serologic such as leukocytosis, ESR, and CRP or pathologic findings), which could have influenced clinicians’ decision-making related to antimicrobial de-escalation or discontinuation and the shortening of antimicrobial regimens." (PMID 39766556, 2024). "The observed correlation between PL and PI coupled with the similar CRP level among the three NAS groups and the absence of leukocytosis might suggest that the presence of PL is secondary to the development of steatohepatitis and not secondary to systemic inflammatory reaction." (PMID 30500848, 2018). "Anemia, leukocytosis, thrombocytopenia and elevated LDH and CRP should raise clinical concern in patients with non-specific symptoms where the suspicion of cancer has been raised, and could possibly guide the physician towards the most likely diagnosis and the best-suited investigational course." (PMID 29197366, 2017).
anemia (1,536 papers, 2003 to 2026). A reduction in the number of red blood cells, the amount of hemoglobin, and/or the volume of packed red blood cells. "After adjusting diagnostic thresholds for anaemia, the area under the curve (AUC) for CRP improved from 0.838 to 0.927." (PMID 41619787, 2026). "Laboratory evaluation showed leukocytosis, elevated C-reactive protein (CRP), elevated troponin, iron-deficiency anemia, and a positive urinalysis." (PMID 41755954, 2026). "Multivariate logistic modeling confirmed that low serum zinc independently predicted anemia risk, alongside transferrin saturation and C- reactive protein levels." (PMID 41599845, 2026). "Laboratory testing for ferritin, transferrin, transferrin receptor and CRP can help distinguish between inflammation-induced anemia and iron-deficiency related anemia but rarely allows for a definitive diagnosis in intermediate cases." (PMID 40636681, 2025). "Anaemia risk rose progressively with inflammation: individuals with log(CRP) near −2 had predicted probabilities below 15%, whereas those with log(CRP) above 4 had probabilities exceeding 25%." (PMID 40968580, 2025). "Logistic models showed that anaemia risk declined sharply with increasing BMI but rose consistently with CRP." (PMID 40968580, 2025). "The complete blood panel demonstrated anemia, thrombocytopenia, micronutrient deficiencies, mildly impaired renal function, and markedly elevated CRP, confirming a systemic inflammatory state consistent with the clinical picture." (PMID 41170218, 2025). "D-dimer/albumin captures hypercoagulability and inflammation; immobility and central venous catheters are established clinical risk factors; and elevated CRP, anemia, and thrombocytosis reflect pro-thrombotic states in cancer." (PMID 41156207, 2025). "Our primary outcome parameter was hemoglobin level at 12 months of intervention, and the secondary outcomes included anemia prevalence and iron deficiency anemia based on serum ferritin (corrected for C-reactive protein) and growth." (PMID 40806102, 2025). "At admission, his blood tests showed microcytic anemia (Hb 6.6 g/dL, normal range 13 to 16 g/dL) with iron deficiency (9.0 mcg/dL, reference values 60–160 mcg/dL) and an increase of C-Reactive Protein (CRP 27 mg/dL, normal range < 0.5 mg/dL)." (PMID 40559193, 2025). "A study indicates that inflammatory markers like C-reactive protein (CRP) and interleukin-6 (IL-6) are elevated in frail individuals and linked to anemia and poor health outcomes." (PMID 40337739, 2025). "Female gender, low BMI, ossification, elevated ESR, and abnormal CRP levels were identified as independent risk factors for anemia in AS." (PMID 39908327, 2025). "It is also recommended to correlate zinc levels with CRP and albumin levels and to use caution when diagnosing zinc deficiency in the background of high CRP >20 mg/L, hypoalbuminemia, or anemia." (PMID 38975455, 2024). "The risk of anemia with micronutrient deficiencies were less likely among those with high CRP levels (aPR (95% CI):0.8, (0.6–0.9))." (PMID 38236794, 2024). "Other medical conditions during pregnancy, like anemia and elevated C-reactive protein (CRP) levels, were associated with increased odds of preterm birth, with ORs of 1.6 and 2.0, respectively." (PMID 38257966, 2024). "The DNR/POLST group had more underlying diseases, and laboratory findings included anemia, hyperbilirubinemia, hypoalbuminemia, and higher CRP." (PMID 38355511, 2024). "Andersen and colleagues found that low serum ferritin and folate, malaria, and high CRP were risk factors for anemia among WRA in Ethiopia." (PMID 38448918, 2024). "IBD is associated with several biochemical alterations as increases in inflammatory markers, including C-reactive protein (CRP), fecal calprotectin (f-cal) and lactoferrin, vitamin and mineral deficiencies, and anemia." (PMID 39061667, 2024).